OR4F17 (olfactory receptor family 4 subfamily F member 17)
Description:
Odorant receptor.
Synonyms: OR4F11P; OR4F18; OR4F19
Tractability: Small molecule: it belongs to a druggable protein family. Antibody: its Gene Ontology location is reachable by antibodies, with high confidence; UniProt places it where antibodies can reach, with medium confidence; UniProt predicts a signal peptide or a membrane-spanning region.
Gene: Protein-coding gene on chromosome 19 (107,104 to 117,102, forward strand). Ensembl gene ENSG00000176695.
Subcellular location: Cell membrane
Pathways (Reactome):
Sensory Perception: Expression and translocation of olfactory receptors; Olfactory Signaling Pathway
Gene Ontology:
Molecular function: olfactory receptor activity; G protein-coupled receptor activity
Biological process: detection of chemical stimulus involved in sensory perception of smell; G protein-coupled receptor signaling pathway
Cellular component: plasma membrane; membrane
Genetic constraint (gnomAD): Loss-of-function variants: 0 observed, 1.72 expected, observed/expected ratio (o/e) 0, 90% interval 0 to 1.47. That is too few expected variants to judge how well the gene tolerates losing a copy. Missense variants: 0 observed, 43.39 expected, observed/expected ratio (o/e) 0, 90% interval 0 to 0.069. Synonymous variants: 1 observed, 18.25 expected, observed/expected ratio (o/e) 0.0548, 90% interval 0.018 to 0.26.
Homologues: Orthologues: mouse Or4f4-ps1 (82% identical), rat Or4f4b (82% identical), mouse Or4f17 (81% identical), mouse Or4f4b (81% identical). Paralogues in human: OR4F4 (99% identical), OR4F5 (99% identical), OR4K1 (60% identical), OR4F6 (59% identical), OR4F15 (58% identical), OR4K15 (58% identical), OR4F16 (57% identical), OR4F21 (57% identical), OR4F29 (57% identical), OR4F3 (57% identical), OR4K13 (57% identical), OR4K14 (57% identical), and 116 more.
Diseases named in the same sentence as OR4F17 in open-access papers:
OR4F17 is named in the same sentence as 2 diseases in open-access papers, as found by Europe PMC text mining. Sharing a sentence is not in itself a finding about the gene and the disease. The quoted sentences say what the papers report.
chronic hepatitis B (1 paper, 2016). "We assessed OR4F3 and OR4F17 copy number levels by absolute qPCR in healthy controls (Con, n = 5), chronic hepatitis B patients (CHB, n = 10), hepatitis B virus-liver cirrhosis patients (HBV-LC, n = 10), and hepatitis B virus- HCC patients (HBV-HCC, n = 10)." (PMID 26769853, 2016).
OR4F17 also shares sentences with these, for which no sentence is quoted: liver cirrhosis (1 paper).